MTOR (mechanistic target of rapamycin kinase)
Diseases named in the same sentence as MTOR in open-access papers (continued):
Sharing a sentence is not in itself a finding about the gene and the disease.
diabetes (558 papers, 2006 to 2026). "These inhibitors of mTOR, which also target tyrosine kinases, are associated with hyperglycemia, a characteristic feature of diabetes." (PMID 39996906, 2025). "Dysregulation of mTOR signaling is implicated in the progression of cancer, diabetes, and the aging process." (PMID 40280130, 2025). "Aberrant mTOR signaling is commonly associated with a wide range of diseases, including cancer, diabetes, obesity, various neurological disorders and other pathologies." (PMID 41469379, 2025). "Dysregulation of mTOR signaling has been implicated in several major diseases, including diabetes, cancer, and neurological disorders." (PMID 40676806, 2025). "Dysregulation of mTOR signaling has been implicated in metabolic disorders such as diabetes and obesity." (PMID 41415839, 2025). "Immunosuppressants and/or antineoplastics such as inhibitors of mammalian target of rapamycin (mTOR), calcineurin inhibitors, and glucocorticoids promote insulin resistance, worsen glycaemia, and/or increase the risk of diabetes." (PMID 40793247, 2025). "The hyperactivation of insulin receptor substrate 1 (IRS-1), an important upstream regulator of mTOR, has also been linked to diabetes." (PMID 39770519, 2024). "The mTOR signaling pathway is also enriched in our comprehensive analysis, with mTOR activation implicated in a spectrum of pathological conditions, including obesity, diabetes, and CVD." (PMID 39411310, 2024). "Targeted genes such as PI3K/AKT/mTOR are commonly activated in solid tumors and associated with insulin resistance in diabetes conditions resulting in hyperglycemia." (PMID 39410536, 2024). "Dysregulation of mTOR occurs following inhalation exposures and has also been implicated in many diseases such as cancer, obesity, cardiovascular disease, diabetes, asthma, and neurodegeneration." (PMID 38711460, 2024). "In this review, we explore and discuss the molecular connection between mTOR signaling and polyploidy along with its association with cancer, diabetes and aging." (PMID 38539200, 2024). "In db/db mice, the levels of phospho-mTOR and the ratio of phospho-mTOR/mTOR were significantly increased in comparison to WT mice, indicating that the mTOR pathway is activated in diabetes-associated kidney dysfunction." (PMID 39902076, 2024). "Numerous studies have shown that MTOR is an important gene in the insulin signalling pathway and susceptibility to type 2 diabetes mellitus." (PMID 38932873, 2024). "Multivariate analysis of the parameters associated with the occurrence of microvascular complications in subjects with diabetes showed that the mTOR and HbA1c values were independently associated factors." (PMID 39261960, 2024). "Over the past two decades, mTOR has been shown to govern several essential cell functions, and dysregulated mTOR signaling has been linked to cancer, diabetes and aging." (PMID 38539200, 2024). "Due to mTOR’s central role in controlling cell growth and metabolism, mTOR signaling dysregulation is implicated in multiple diseases, including cancer, diabetes, and neurological disorders." (PMID 39141345, 2024). "It has also been demonstrated that RES directly inhibits mTORC-1 phosphorylation, thereby decreasing mTORC-1 activity and reducing the risk of diabetes associated with hyperactive mTOR." (PMID 39456808, 2024). "It is noteworthy that the majority of the trials excluding patients with diabetes involve PIK3CA or mTOR inhibitors, both of which are known to cause hyperglycemia." (PMID 38778365, 2024). "Embedded in a complex network of signaling pathways, mTOR dysregulation is implicated in the onset and progression of a range of human diseases, including metabolic disorders such as diabetes and cardiovascular diseases, as well as various cancers." (PMID 38892329, 2024).
diabetes (continued). "Different forms of illness such as cancer, neurodegenerative disorders, cardiovascular diseases, diabetes are associated with dysregulated mTOR signaling due to imbalance of nutrient and energy demands, therefore, suggesting malfunctioned autophagy." (PMID 38711460, 2024). "Dysregulated mTOR signaling has been implicated in the progression of cancer, diabetes and the aging process." (PMID 38539200, 2024). "Dysfunction of mTOR signaling is associated with many diseases, including diabetes and neurological diseases." (PMID 39629074, 2024). "The mTOR/S6K signaling cascade is implicated in various pathological conditions, including diabetes, cancer, and obesity, as it actively stimulates protein synthesis and cell growth." (PMID 39513867, 2024). "Inhibition of the mTOR complex has been associated with the attenuation and alleviation of various metabolic and- inflammatory diseases such as neurodegeneration, diabetes, and metabolic syndrome." (PMID 37076659, 2023). "Deregulated mTOR signaling is implicated in the progression of cancer and diabetes, as well as the aging process." (PMID 38152126, 2023). "The mechanistic target of rapamycin (mTOR) is a crucial regulator of cellular metabolism and is implicated in cancers and diabetes." (PMID 36983043, 2023). "Inhibiting HMGB1 reduced apoptosis and injury in podocytes and delayed the deterioration of glomerular function caused by diabetes by activating the Akt/mTOR signaling pathway and inhibiting autophagy." (PMID 37065747, 2023). "The stratified analysis results are plausible because the PA-mTOR association was more apparent among participants with less influence from obesity and diabetes, factors that can affect the mTOR pathway activities." (PMID 36895729, 2023). "Persistent mTOR stimulation is linked with a wide range of diseases such as diabetes, obesity, cardiovascular diseases, cancer, autoimmune diseases and metabolic disorders." (PMID 37920252, 2023). "Activation of mTOR signaling is proposed as a cause of diabetes-associated glomerular injury as mTOR regulates the podocyte size." (PMID 37870960, 2023). "As a key regulator of cell metabolism and growth in response to nutritional and hormonal stimuli, mTOR deregulation has been implicated in many disease states, including diabetes, obesity and NAFLD." (PMID 35428314, 2022). "Obesity, B blood group, hypertension- or diabetes-induced ESRD, diabetes history, deceased donor, and mTOR inhibitor use decreased the risk of PTSC incidence." (PMID 36505816, 2022). "The dysregulation of energy metabolism pathways can also be linked to the differential regulation of MTOR and protein glycosylation pathways, an association that has already been investigated in the past for conditions such as obesity, diabetes and cancer." (PMID 36181557, 2022). "Mammalian target of rapamycin (mTOR) is a serine/threonine protein kinase that orchestrates metabolism and physiological responses and is associated with human diseases such as diabetes, obesity, and cancers." (PMID 36505429, 2022). "The proteogenomic analysis identified that MTOR mutations were positively associated with the PDAC patients with diabetes (Fisher’s exact test, P = 0.03)." (PMID 36434634, 2022). "Evidence has shown that dysregulation of mTOR signalling is linked to many human diseases, including diabetes, neurodegenerative diseases, and cancer." (PMID 36308410, 2022). "mTOR signaling dysfunction is linked to a variety of diseases, including cancer, cardiovascular disease, neurodegenerative diseases, and diabetes." (PMID 35001007, 2022). "The overexpression of mTOR is often associated with tumor progression, diabetes, and neurodegenerative disorders." (PMID 35267644, 2022). "Diabetes mellitus (DM) can cause desmin to become dysregulated, following episodes of nitrosative stress, through the activation of the iNOS/mTOR/TIMP-1 pathway, thereby stimulating collagen deposition in the myocardium." (PMID 35625721, 2022).
diabetes (continued). "The mammalian/mechanistic target of rapamycin (mTOR) protein is an important growth regulator and has been linked with multiple diseases including cancer and diabetes." (PMID 35788771, 2022). "Another recent study, pointed out that polymorphism in PI3K/AKT/mTOR genes were strongly associated with the risk of type 2 diabetes mellitus (T2DM) and its resulting hyperglycaemia." (PMID 35327652, 2022). "Secondly, genetic variants in the mTOR pathway have been identified with the single nucleotide polymorphisms (SNPs) rs7211818 and rs9674559 showing a relationship with the risk of type 2 diabetes mellitus (T2DM)." (PMID 35013125, 2022). "On one hand, numerous studies have demonstrated that mTOR activation was implicated in metabolic diseases, such as obesity and diabetes." (PMID 35712246, 2022). "Accordingly, dysregulation of the mTOR signaling pathway has been implicated in many human diseases, such as diabetes, cancer, obesity, and nervous system diseases." (PMID 35170378, 2022). "Dysregulation of mTOR signaling is tightly associated with many human diseases, such as obesity, diabetes, cancers, and neuronal disorders, making mTOR an ideal therapeutic target." (PMID 33670113, 2021). "We further discuss pharmacological approaches to treat diabetes complications linked to mTOR deregulation." (PMID 35178356, 2021). "The current paper aims to discuss the possible implications of SGLT2 inhibition on chronic activation of mTOR as a common pathogenic mechanism between AD and diabetes, according to the recent research findings." (PMID 34069618, 2021). "On the other hand, dysregulation of mTOR signaling is linked to cancer, diabetes and the aging process." (PMID 34832986, 2021). "For instance, over-nutrition can cause the hyperactivation of mTOR signaling, which is associated with diabetes." (PMID 33467535, 2021). "Studies have also shown that mTOR inhibition associates with autophagy activation, and in contrast mTOR hyperactivation can increase lipid production that parallels obesity, diabetes, and fatty liver disease." (PMID 34829868, 2021). "Rapamycin protects against AA induced nephropathy by activating the mTOR autophagy axis.The Usmg5, known as diabetes-associated protein in insulin-sensitive tissues (DAPIT), is a part of the mitochondrial ATP synthase." (PMID 34685389, 2021). "Aging‐related disorders such as cancers, diabetes, cardiovascular, and neurodegenerative diseases, as well as normal aging, have been linked to dysregulated signaling of the mechanistic target of rapamycin (mTOR) pathway." (PMID 34453483, 2021). "Diabetes and AD are both linked to a condition of chronically activated mTOR, resulting in chronic inhibition of autophagic and lysosomal processes that affect the long-term functioning of the brain, pancreas, heart, kidney, and other organs." (PMID 34069618, 2021). "The hyperactivation of the mTOR pathway by hyperglycemia in diabetes can cause insulin resistance due to the desensitization event caused by IRS-1 Ser 636/639 phosphorylation." (PMID 33467535, 2021). "Other signaling pathways are implicated in diabetes, such as the mammalian target of Rapamycin (mTOR) in mTOR complex 1 (mTORC1) and mTOR complex 2 (mTORC2), which appear to be deregulated in the development and progression of diabetes." (PMID 32423098, 2020). "Mammalian target of rapamycin (mTOR) is a crucial regulator of cell growth and metabolism and has been implicated in aging and many diseases, including cancer, diabetes and neurological diseases." (PMID 31879284, 2020). "As such, mTOR protein is a central metabolic integrator and is dysregulated in type 2 diabetes and diabetes-associated co-morbidities." (PMID 32978410, 2020). "High levels of free fatty acids are known to cause constitutive mTOR signal activation, a process associated with diseases such as diabetes and obesity." (PMID 32121602, 2020).
diabetes (continued). "Sustained mTOR stimulation is associated with various diseases, such as diabetes, obesity, cardiovascular disease, cancer, and autoimmune diseases." (PMID 33343350, 2020). "Deregulated mTOR signaling is implicated in a variety of disorders, such as cancer, obesity, diabetes, and neurodegenerative diseases." (PMID 33065976, 2020). "Mammalian target of rapamycin (mTOR) regulates cellular metabolism and is strongly implicated in the development of cancer and diabetes." (PMID 32069925, 2020). "Dysregulation of mTOR signaling has been implicated in cancer, diabetes, obesity, neurological diseases and genetic disorders." (PMID 32188029, 2020). "Because glomerular hypertrophy has been associated with mTOR activation in diabetes, we also measured mTOR activation in the glomerular tuft area by quantifying pS6RP staining." (PMID 32597007, 2020). "It has been established that mTOR plays a central role in cellular processes and implicated in various cancers, diabetes, and in the aging process with very poor prognosis." (PMID 31075885, 2019). "Meanwhile, the increase of TXNIP expression by selective loss of mechanistic target of rapamycin (mTOR) in mouse β-cells exacerbates the development of diabetes." (PMID 31623194, 2019). "mTOR plays a central role in regulating many fundamental cell processes in eukaryotic cell, from protein synthesis to autophagy, and deregulated mTOR signaling is implicated in the progression of cancer and diabetes, as well as the aging process." (PMID 30705773, 2019). "Dysregulation of the mTOR signaling pathway has been associated with several major disease states (e.g., diabetes, obesity, cancer, and cognitive defects)." (PMID 31491954, 2019). "Dysregulation of mTOR is implicated in a number of human pathologies, including diabetes and obesity." (PMID 30755615, 2019). "We showed that insulin treatment is associated with higher IGF1R and p-mTOR tumor expression in women with diabetes." (PMID 29486734, 2018). "Dysregulation of mTOR signaling has been implicated in many human diseases including obesity, diabetes, cancer, fatty liver diseases, and neuronal disorders." (PMID 28434145, 2018). "We found that insulin treatment in women with diabetes is associated with p-mTOR tumor expression, and in premenopausal women with IGF1R tumor expression." (PMID 29486734, 2018). "Nevertheless, studies have revealed a novel role for mTOR in CVDs like ischemia reperfusion (I/R) injury, heart failure, and its associated risk factors including diabetes and aging." (PMID 30305865, 2018). "Dysregulation of mTOR signaling has been implicated in many human diseases, including obesity, diabetes, cancer, and neuronal disorders." (PMID 28434145, 2018). "Dysregulation of the mTOR pathway has been implicated in a number of human diseases such as cancer, diabetes, obesity, neurological diseases, and genetic disorders." (PMID 30526568, 2018). "On the other hand, due to excess nutrients supply, hyperactivation of mTOR has also been implicated to cause diabetes." (PMID 28659828, 2017). "Persistent mTOR stimulation is linked to various diseases such as diabetes, obesity, cardiovascular diseases, cancer, and autoimmune disorders." (PMID 28690762, 2017). "This is further supported by the in vivo results that KCa3.1 deficiency reversed diabetes suppressed autophagy through inhibition of the activation of the PI3K/Akt/mTOR signaling pathways in diabetic mice." (PMID 27029904, 2016). "Dysregulation of the mTOR pathway has been implicated in a number of human diseases such as obesity, diabetes mellitus, and cardiovascular diseases." (PMID 27057269, 2016). "This study revealed another interesting aspect concerning the activation of the mammalian target of rapamycin (mTOR), a key kinase controlling cell growth and proliferation and implicated in many human diseases including cancer and diabetes." (PMID 25671136, 2014).
diabetes (continued). "For example, circadian disruption is a recognized risk factor for development of cancer, diabetes and obesity; noteworthy, the mTOR pathway plays an important role in all these diseases." (PMID 24481314, 2014). "Considering the induction of mTOR by high glucose levels, the mTOR pathway is likely implicated in the induction of brain protein aggregation in diabetes." (PMID 24393531, 2014). "When diabetes is caused by high mTOR activity, then it is associated with complications, diseases and shortened life span." (PMID 22683661, 2012). "Deregulation of mTOR is linked to diabetes through excess food and energy intake, and weight gain which is linked to cardiovascular disease and other adverse health conditions." (PMID 22680924, 2012). "The mTOR pathway plays an important role in regulating cell growth and proliferation and its deregulation is associated with many human cancers and diabetes." (PMID 21437186, 2011). "Both diabetes and obesity show a much more significant association with the mTOR interactome than any pro-inflammatory disease other than lupus." (PMID 18980674, 2008). "Management of post-transplant diabetes can be challenging, as immunosuppressive drugs such as glucocorticoids, calcineurin inhibitors, and mTOR (mammalian target of rapamycin) inhibitors are associated with induction of hyperglycemia or worsening of glucose control." (PMID 39768911, 2024). "Dysregulation of the mTOR pathway is implicated in a spectrum of pathophysiological conditions, ranging from premature aging and neurodegenerative diseases like Alzheimer’s to metabolic disorders such as diabetes and obesity, as well as cancer." (PMID 38727317, 2024). "Moreover, dysregulation in mTOR is associated with various diseases such as obesity, diabetes, cancer, and neurological diseases." (PMID 39872068, 2024). "Furthermore, it was determined that quercetin alleviates cellular autophagy by downregulating proteins associated with the PI3K/Akt/mTOR pathway, thus mitigating the impact of diabetes on the liver, kidney, and spleen of rats." (PMID 39211336, 2024). "Pharmacological side effects from medications such as corticosteroids, calcineurin inhibitors (CNIs), and mammalian target of rapamycin (mTOR) inhibitors often include hypertension, gaining weight, diabetes, hyperlipidemia, and increased susceptibility to infections." (PMID 38993475, 2024). "mTOR, a serine/threonine kinase, regulates cell growth and proliferation in response to various signals and participates in autophagy regulation; it has been implicated in diabetes mellitus, neurodegenerative diseases, and various cancers." (PMID 39519229, 2024). "The demonstrated familial cosegregation of p.Gln2063ArgfsTer3 with diabetes may suggest variant pathogenicity and a potential association of MTOR with rare MODY cases." (PMID 39201476, 2024). "In addition to the complexity of mTOR-diabetes association, the inhibition of mTOR, as a result of oncological target therapies, is also associated with the onset of hyperglycemia or DM." (PMID 39201476, 2024). "The mTOR signaling pathway plays a key role in contributing to several cell processes, and dysregulation of the mTOR pathway has been implicated in promoting many diseases including cancer, diabetes mellitus, ageing and cardiovascular diseases." (PMID 37626809, 2023). "For example, the mTOR signaling pathway is related to cancer, and AD; IL-8 signaling is associated with inflammation; insulin receptor signaling is linked to diabetes." (PMID 37550674, 2023). "Overall, the different mTOR complexes play important roles in regulating a variety of cellular processes and their dysregulation has been linked to several diseases in humans, including cancer, diabetes, and neurological disorders." (PMID 37830621, 2023). "Dysregulation of mTOR signaling is associated with many diseases, including diabetes and cancer." (PMID 36835331, 2023).